XDH (xanthine dehydrogenase)
Diseases named in the same sentence as XDH in open-access papers (continued):
Sharing a sentence is not in itself a finding about the gene and the disease.
tumor (69 papers, 1989 to 2026). "Studies have shown that xanthine dehydrogenase (XDH)-derived reactive oxygen species (ROS) accelerates tumor growth, and also induces mutations or produces cytotoxic effects concurrently." (PMID 35693733, 2022). "Elevated expression of XDH is associated with tumor infiltration as well as upregulated proinflammatory and immune‐related cytokine expression." (PMID 32009302, 2020). "Tumours with high levels of XDH mRNA were characterised by higher expression of several genes encoding pro-inflammatory and immune cytokines, and increased levels of tumour infiltration with immune cells." (PMID 30104401, 2018). "We found an association between the expression levels of XDH and tumour expression of immune cytokines, as well as higher infiltration of immune and inflammatory cells in tumour tissues." (PMID 30104401, 2018). "Additionally, XDH has been implicated in modulating the tumor immune microenvironment, with early reports indicating positive correlations with CD8+ T-cell infiltration and negative associations with PD1+ immune cells." (PMID 40282409, 2025). "Moreover, the expression of C1QBP and XDH was lower in RCC tumors compared with the tumor-associated normal tissues, and their down-regulation was associated with higher Fuhrman grade." (PMID 35693733, 2022). "The XDH-associated cell signaling pathway may affect immune cell infiltration into the tumor microenvironment." (PMID 34496841, 2021). "A recent study suggested that XDH expression levels are associated with tumor growth." (PMID 32009302, 2020). "Moreover, the XDH-associated signaling pathway may regulate the immune response and tumor-infiltrating immune cells in HCC." (PMID 34496841, 2021). "Importantly, the prognostic value of the XDH-associated immune signature in HCC shed light on XDH might modulate tumor immunity in HCC." (PMID 34496841, 2021). "This study also identified decreased XDH expression in LC that can enhance hypoxanthine levels in the tumor as a critical metabolic alteration with a clinical significance in AN LC patients." (PMID 40075691, 2025). "While most of the genes related to the purine metabolic pathway were upregulated in LC, xanthine dehydrogenase (XDH), which converts hypoxanthine to uric acid, showed a downregulation in the tumor compared to the normal tissues." (PMID 40075691, 2025). "We have clarified that C1QBP promotes RCC cell hypoxanthine catabolism via up-regulating XDH, and apoptosis by modulating XDH mediated ROS generation and pro-apoptotic proteins caspase-3 and bax/bcl2, then affects tumor progression." (PMID 35693733, 2022). "We also reached consistent conclusions that C1QBP inhibited tumor growth and increased expression of XDH and pro-apoptotic related protein in mice orthotopic tumor xenografts model." (PMID 35693733, 2022). "After tumor implantation, XO knock-in (ki) mice showed stronger tumor growth than wild-type (WT) or XDH ki mice." (PMID 34829959, 2021). "XDH expression was analyzed in multiple databases, including Oncomine, the Tumor Immune Estimation Resource (TIMER), the Kaplan–Meier plotter database, the Gene Expression Profiling Interactive Analysis (GEPIA) database, and The Cancer Genome Atlas (TCGA)." (PMID 34496841, 2021). "To understand the mechanistic role of XDH, we performed in-depth analysis of the relationship between XDH expression and tumor-infiltrating immune cells." (PMID 34496841, 2021). "Uric acid, which was transformed by XDH, was found to modulate tumor cell sensitivity to the antimetabolite 5-FU, one of the most commonly used anticancer drugs in the clinic." (PMID 34660806, 2021). "CMT93 tumor volume reached rapidly a larger size in XO ki mice compared to XDH ki or control WT mice." (PMID 31659168, 2019). "Here we show that XO ki and XDH ki macrophages differentially influence the tumor microenvironment, thereby providing a new mechanism by which an imbalance within the enzymatic XO/XDH ratio correlates with an increase of tumor burden." (PMID 31659168, 2019).
tumor (continued). "Collectively, these results indicate that the balance of XO/XDH plays an important role in immune surveillance of tumor development." (PMID 31659168, 2019). "Our study highlights APRT, in addition to XDH, as a source of individual variability in uricogenesis among tumours." (PMID 30104401, 2018). "Lower levels of XDH gene expression were found in tumours of high grade (for HCC: G1 compared with G4, P=0.0021; for HNSCC: G1 compared with G4, P=0.0174)." (PMID 30104401, 2018). "In this study, we showed that low XDH mRNA levels were correlated with higher tumor stages and poorer prognoses in patients with HCC." (PMID 28945217, 2017). "The conversion of XDH to XO has been observed in two tumour types upon the prolonged clamping off of the blood supply to the tumours." (PMID 2765364, 1989). "The enzyme activities of endogenous xanthine dehydrogenase (XDH) and xanthine oxidase (XO) have been measured in 10 different types of mouse tumour and seven normal tissues." (PMID 2765364, 1989). "Interestingly, only XDH, which catalyzes hypoxanthine to uric acid, was downregulated in the tumor tissues." (PMID 40075691, 2025). "XDH protein was significantly higher in LUAD tumor tissues compared to normal counterparts." (PMID 36778128, 2023). "Furthermore, XDH mRNA levels correlated with the numbers of tumor-infiltrated immune cells based on the levels of markers for different immune cell types in HCC." (PMID 34496841, 2021). "Together, these findings suggest that XDH may modulate the infiltration of immune cells into tumor tissues." (PMID 34496841, 2021). "XDH mRNA expression is related to tumor-infiltrating immune cells." (PMID 34496841, 2021). "Some reports have showed that XDH protein expression and activity are much lower in tumor tissues compared to normal counterparts in gastrointestinal, breast, lung, bladder, and ovary tissues, in which XDH protein levels are normally expressed at a higher level." (PMID 32899343, 2020). "Interestingly, the authors reported that XO knock-in mice showed significant increase in tumor growth compared with wild-type or XDH knock-in mice and that these effects were mediated by ROS production by XO knock-in macrophages." (PMID 32518351, 2020). "Tumour grade, however, significantly correlated with the expression levels of XDH: high-grade pancreatic tumours had significantly higher expression levels of XDH (G1 compared with G3, P=0.0006)." (PMID 30104401, 2018). "Interestingly, expression levels of APRT also showed great inter-tumour heterogeneity, yet to a smaller extent than XDH (a more than 102-fold difference between the median expression values in the high compared with low-expressing tumour types)." (PMID 30104401, 2018). "XDH transcript levels were negatively correlated with tumor stages in HCC, suggesting that XDH may be a useful clinical indicator in patients with HCC." (PMID 28945217, 2017). "Indeed, decreased XDH may mediate immune evasion by affecting the immune cell infiltration into the tumor microenvironment." (PMID 35664305, 2022). "Finally, the balance of oxidase and xanthine dehydrogenase (XDH) determines the tumor growth." (PMID 34917077, 2021). "Consistently, immunohistochemistry analysis of tumor tissues and matched adjacent normal tissues from a cohort of 87 Chinese LUAD patients showed enhanced staining of XDH in LUAD tissues." (PMID 36778128, 2023). "Our findings suggest that C1QBP is a novel mediator of RCC tumor progression and targeting C1QBP/XDH provides a potential treatment strategy for RCC." (PMID 35693733, 2022). "In HCC, a positive correlation was found between XDH expression and CD8 + T-cell infiltration in the analysis of both the TIMER database and IHC staining of immune cell markers in HCC tumor tissues." (PMID 34496841, 2021). "Neither Sod1−/− XO-locked-type nor Sod1−/− XDH-stable-type double-mutant mice exhibited tumor formation in the liver or other tissues at 7–12 months of age (data not shown)." (PMID 33805516, 2021).
tumor (continued). "We observed strikingly increased expression of Fpr2 in XO mice, a marker for M1 macrophages and/or inflammation, whereas XDH ki mice expressed higher levels of arginase (arg), a marker for M2 macrophages within the tumor." (PMID 31659168, 2019). "To investigate if bone-marrow-derived cells or radio-resistant non-hematoipoietic cells are responsible for the increased tumor growth in XO ki mice, we generated chimeric mice by transplantation of bone marrow (BM) from WT, XO ki and XDH ki mice into lethally irradiated WT mice (950 Rad)." (PMID 31659168, 2019). "Importantly, XDH-overexpressing MHCC97H cells resulted in a reduced numbers of metastatic nodules in the lungs but did not affect subcutaneous tumor growth, indicating that XDH may act as a tumor metastasis suppressor gene in HCC." (PMID 28945217, 2017). "This rise was not due to conversion of HDX (Xanthine dehydrogenase) to XO, since the HDX activity was significantly lower in tumor versus healthy tissue." (PMID 32899343, 2020).
cardiovascular disease (68 papers, 2009 to 2025). "Nrf2 can contribute to cardiovascular disease by inducing undesirable effects on vascular function and remodeling, such as by increasing the expression of xanthine dehydrogenase (XDH), which converts hypoxanthine and xanthine into uric acid and superoxide anion." (PMID 40427486, 2025). "As a future perspective, studies in XDH knockout-mice may be conducted to reveal the importance of XDH to XO conversion for the protective effects of inorganic nitrite in mice with cardiovascular disease." (PMID 35327532, 2022).
infection (26 papers, 2014 to 2025). The state of being infected such as from the introduction of a foreign agent such as serum, vaccine, antigenic substance or organism. "Upon infection of tea plant with C. camelliae, we observed alterations in the expression of fungal transcripts, including those of many genes associated with caffeine metabolism, such as those encoding various transporters, xanthine dehydrogenase, and urate oxidase (UOX)." (PMID 36687674, 2022). "According to these findings, urate produced by XDH in infected cells is transferred for its further oxidation by UOX to the uninfected cells in the infection zone." (PMID 36088455, 2022). "During infection, the expression of Serine 3-dehydrogenase and xanthine dehydrogenase was significantly up-regulated over time in the highly aggressive V. dahliae isolate." (PMID 33922492, 2021). "In our study, the expression of Serine 3-dehydrogenase, pyruvate dehydrogenase E1 component subunit beta, xanthine dehydrogenase, and myo-inositol dehydrogenase were upregulated in V. dahliae with potato extracts elicitation and during infection." (PMID 33922492, 2021). "Furthermore, the preferential expression of XDH in the infection zone of the nodules reinforces the hypothesis of its involvement in the defense responses which occur at the beginning of the symbiotic process." (PMID 33013954, 2020). "Transcription of zeaxanthin epoxidase chloroplastic (ZEP, Solyc02g090890), xanthoxin dehydrogenase (XDH, Solyc04g071960), and violaxanthin de-epoxidase (VDE, Solyc04g050930) were down-regulated by DC3000 infection, while ZEP and XDH were up-regulated by RL treatment." (PMID 25765075, 2015). "Furthermore, XOR inhibitors, as already mentioned, increase the concentration of hypoxanthine in the blood, which is also a factor in helping the conversion of XDH to XO at the site of infection." (PMID 37298917, 2023).
bacterial infection (4 papers, 2018 to 2024). "Consistent with this postulation, previous work has found increased abundance of xanthine dehydrogenase in L. intracellularis challenged pigs, an enzyme which regulates production of ROS and nitric oxide synthase to control bacterial infections." (PMID 34147126, 2021). "The authors believe that in mammals, the conversion from XDH to XO is specific to specialized mammary glands (extremely weak activity in humans) and salivary glands, where the highly reactive reaction intermediate oxo-thiocyanate acts as a defense against bacterial infection during milking." (PMID 37298917, 2023).
neurodegenerative disease (4 papers, 2020 to 2025). A disorder of the central nervous system characterized by gradual and progressive loss of neural tissue and neurologic function. "Xanthine dehydrogenase/oxidase blockade might reduce risk of neurodegenerative disease." (PMID 37195983, 2023). "Blockade of xanthine dehydrogenase/oxidase or its effects, regardless of indication, was associated with a modestly reduced risk of all three neurodegenerative diseases." (PMID 37195983, 2023).
XDH also shares sentences with these, for which no sentence is quoted: diabetes (82 papers); chronic kidney disease (55); metabolic syndrome (47); kidney disease (34); metabolic disorders (32); chronic heart failure (29); coronary artery disease (28); type 2 diabetes (25); myocardial infarction (21); depression (19); Hyperglycemia (18); Hepatic steatosis (16); heart disease (10); ischemic stroke (10); cardiac hypertrophy (8); diabetic nephropathy (8); Arthritis (7); Cerebral ischemia (7); Hyperinsulinemia (7); hyperlipidemia (7); hypertriglyceridemia (7); sarcopenia (7); type 1 diabetes (7); coronary artery spasm (6); gastric cancer (6); Hepatitis (6); inflammation (6); ischemia reperfusion injury (6); liver dysfunction (6); non-alcoholic steatohepatitis (6).
A further 247 diseases each share a sentence with XDH in 6 papers or fewer.